ARNT2 (aryl hydrocarbon receptor nuclear translocator 2)
Diseases named in the same sentence as ARNT2 in open-access papers (continued):
Sharing a sentence is not in itself a finding about the gene and the disease.
melanoma (2 papers, 2022). A malignant, usually aggressive tumor composed of atypical, neoplastic melanocytes. "We found a concordant relationship between DNA methylation and transcriptional levels for genes from the malignancy (Pyroxd2 and Ptgfrn) and metastasis (Arnt2, Igfbp4 and Ptprf) signatures, which were both also correlated with melanoma prognosis." (PMID 35606887, 2022). "In the metastasis signature, Arnt2 and Igfbp4 genes, highly expressed and hypomethylated only in 4C11 + metastatic melanoma cells compared to melan-a, 4C and 4C11− cells, had their expression significantly increased in melan-a, 4C and 4C11− cells after 5azaCdR and 5azaCdR + TSA treatment." (PMID 35606887, 2022).
microcephaly (2 papers, 2017 to 2018). A congenital or acquired developmental disorder in which the circumference of the head is smaller than normal for the person's age and sex. "The importance of Arnt2 has also been demonstrated in a case study of a family with a nonsense mutation in Arnt2, where children exhibited microcephaly and delayed or loss of myelination." (PMID 30231889, 2018). "A loss-of-function mutation of ARNT2 in humans results in Webb–Dattani syndrome, with characteristic features such as microcephaly, visual impairment and urinary abnormalities." (PMID 27188386, 2017).
pituitary tumor (2 papers, 2012 to 2016). A benign or malignant neoplasm affecting the pituitary gland. "The destabilization of AhR would naturally imbalance assembly of AhR/ARNT complex and it has been shown that levels of either ARNT or ARNT2, but not both, are devoid in AIP-deficient mouse pituitary tumors." (PMID 23300914, 2012).
alcoholism (1 paper, 2021). "Further in the line are genes participating in circadian clock function such as ARNT, ARNT2, and PER2 which have been implicated in anxiety disorders–alcohol dependence comorbidity and D-box binding protein gene (Dbp) supposedly influencing the risk for both bipolar disorder and alcoholism." (PMID 34201295, 2021).
atrial fibrillation (1 paper, 2021). A disorder characterized by an electrocardiographic finding of a supraventricular arrhythmia characterized by the replacement of consistent P waves by rapid oscillations or fibrillatory waves that vary in size, shape and timing and are accompanied by an irregular ventricular response. "For example, the aryl hydrocarbon receptor nuclear translocator two gene (ARNT2) was identified by GWAS for atrial fibrillation and is a treatment cASE gene in CMs for insulin." (PMID 33988505, 2021).
basal cell carcinoma (1 paper, 2017). A carcinoma involving the basal cells. "ARNT2 (Cluster 5), BRAF (Cluster 5), and PAK7 (Cluster 5) were mapped to “Renal cell carcinoma;” APC (Cluster 5), BRAF (Cluster 5), and GSK3B (Cluster 2) were mapped to “Endometrial cancer;” and APC (Cluster 5) and GSK3B (Cluster 2) were mapped to “Basal cell carcinoma” in our results." (PMID 28445522, 2017).
brain cancer (1 paper, 2017). A primary or metastatic malignant neoplasm affecting the brain. "At least five of them (ARNT2, NEUROD1, NR1I2, HOXC9, NR4A2) are associated with brain cancer in previous studies." (PMID 29033978, 2017).
brain tumor (1 paper, 2017). "For instance, in brain tumor cell lines, ARNT2 can form functional HIF complexes by co-binding with other factors controlling hypoxic responses of the human EPO enhancer." (PMID 29033978, 2017).
breast invasive carcinoma (1 paper, 2024). "Comparing ARNT2 mRNA levels in tumor and normal tissues from the TCGA and GTEx database, we found that ARNT2 levels were elevated in several cancer types including breast invasive carcinoma (BRCA), pancreatic adenocarcinoma (PAAD), and skin cutaneous melanoma (SKCM)." (PMID 39184078, 2024).
breast tumors (1 paper, 2014). "We observed that MYB has an essential partner gene—ARNT2—that is low in non-tumor component but is up-regulated in breast tumors." (PMID 24639887, 2014).
colon cancer (1 paper, 2024). "We confirmed that ARNT2 protein and mRNA were repressed in other cell lines including the human retinal pigment epithelial cell line ARPE-19 and that human colon cancer cell line DLD1 that had elevated MYC." (PMID 39184078, 2024).
embryonic carcinoma (1 paper, 2022). "Whereas the associated AhR heterodimerization partner ARNT2, as well as ARNT1, were up-regulated after human motor neuron differentiation from hiPSCs, only ARNT2 was up-regulated in neurons differentiated from murine embryonic carcinoma cells P19." (PMID 35890127, 2022).
experimental autoimmune encephalomyelitis (1 paper, 2018). An autoimmune demyelinating disease of the central nervous system that is produced experimentally in animals by the injection of homogenized brain or spinal cord in Freund's adjuvant. "To characterize its potential to influence inflammatory neurodegeneration, we examined ARNT2 expression in the experimental autoimmune encephalomyelitis (EAE) model of MS and characterized mediators that influence ARNT2 expression as well as plausible partners and targets." (PMID 30231889, 2018).
Infertility (1 paper, 2010). "Thus, it is intriguing to conceive that also ARNT2 may play an important role in the pathogenesis of infertility in AZFc deleted patients." (PMID 20576090, 2010).
nasopharyngeal carcinoma (1 paper, 2022). A carcinoma arising from the nasopharyngeal epithelium. "In this article, we collected a large amount of ARNT2 expression data in NPC and nonnasopharyngeal carcinoma tissues or cell lines through public datasets." (PMID 36203533, 2022).
neuroblastoma (1 paper, 2021). Neuroblastoma (NB) is the most common solid, extracranial childhood tumor. "ARNT2 and PBX3 expressions were lower in ES cell line RD-ES than neuroblastoma cell line SH-5Y5Y (p < 0.001)." (PMID 33924679, 2021).
preeclampsia (1 paper, 2018). Preeclampsia is a hypertensive disorder of pregnancy that is characterized by new-onset hypertension with proteinuria presenting after 20 weeks of gestation, and depending on mild or severe forms may initially present with severe headache, visual disturbances, and hyperreflexia. "In the “BCL6-ARNT2” pathway, which is activated only in preterm preeclampsia, ischemic stress of the trophoblast coupled with BCL6 and ARNT2 overexpression increases FLT1 expression." (PMID 30135684, 2018). "A permutation test showed that BCL6 overexpression in ischemia mimicked overall expression changes of module M1 and M2 genes in preterm preeclampsia, while ARNT2 overexpression in ischemia (and also in hypoxia) mimicked the up-regulation of module M2 genes in term and preterm preeclampsia." (PMID 30135684, 2018). "Alternating O2 concentrations combined with ARNT2 or BCL6 overexpression led to the dysregulation of 11 genes (5 in the M2 and 3 in the M1 modules), including LEP, FLT1, and ENG, similar to preeclampsia." (PMID 30135684, 2018). "There were 9 genes (6 in the M2 and 3 in the M1 modules) dysregulated in BeWo cells, including FLT1, ARNT2, and ZNF554, similar to preeclampsia." (PMID 30135684, 2018). "Among the transcription regulatory genes in module M2, ARNT2, BCL6, and JUNB were highly expressed in preterm but not in term preeclampsia, suggesting that these might play a role only in the pathology of preterm cases." (PMID 30135684, 2018).
Rett syndrome (1 paper, 2015). A severe neurodevelopmental disorder affecting the central nervous system.
Strabismus (1 paper, 2021). A misalignment of the eyes so that the visual axes deviate from bifoveal fixation. "As a result, we found three genes (ARID1B, ARNT2, COL4A1) intersected with the HPO strabismus gene list." (PMID 33435129, 2021).
cancer (18 papers, 2012 to 2025). A tumor composed of atypical neoplastic, often pleomorphic cells that invade other tissues. "The function and expression of ARNT2 in cancer seems to be tissue-dependent, and the underlying mechanisms are yet to be determined." (PMID 41295250, 2025). "Our study found multiple genes in the cancer pathway that are associates with the progression or suppression of cancer such as laminin, Tgfβ3, Hhip, Arnt2 and Mmp2." (PMID 32330152, 2020). "Some HIFs, such as HIF1A, ARNT, EPAS1, and HIF3A, were linked with unfavorable outcomes for pan-cancer, while two HIFs including ARNTL and ARNT2 were associated with favorable outcomes in pan-cancer." (PMID 33299416, 2020). "However, the upregulation of ARNT2 was associated with a better prognosis of patients, and its exogenous overexpression can inhibit the proliferation and aggressiveness of cancer cells in oral squamous cell carcinoma, liver cancer, and gastric cancer." (PMID 36203533, 2022). "Further phenotypic studies revealed that overexpression of ARNT2 has tumor-suppressive abilities reflected in lower proliferation, migration, and invasion, and higher apoptosis in cancer cell lines and reduced tumor growth in vivo." (PMID 37958512, 2023). "ARNT2 positively correlated target genes were clustered in pathways in cancer, while negatively correlated target genes were enriched in immune-related pathway." (PMID 36203533, 2022). "Aryl hydrocarbon receptor nuclear translocator 2 (ARNT2) has been extensively studied in other cancer species, but little has been explored in NPC." (PMID 36203533, 2022). "Among them, HIF3A and EPAS1 are significantly downregulated, whereas ATNTL and ARNT2 show minimal expression changes in most cancer types." (PMID 33299416, 2020). "The role of ARNT2 in cancer is controversial and appears to be tissue specific." (PMID 39184078, 2024). "Subsequently, we identified five genetic variants in known cancer-related genes (located within SIPA1, ADCY7 and ARNT2) that could be associated with cancer mortality residuals corrected for confounding factors." (PMID 32661568, 2020). "GLI3, ARNT2 and HGF showed predominantly nuclear staining in some cancer cells, while in others, the staining was predominantly cytoplasmic." (PMID 24988459, 2014). "In terms of the genes that are exclusively affected by tumor-specific somatic TE insertions, we also observed the enrichment of affected genes in the cancer pathway (due to tumor-specific TE insertions in genes such as COL4A6, PLCB4, ARNT2, LRP5, NCOA3, and CTNNA2)." (PMID 35013466, 2022). "ARNT2 is overexpressed in NPC and may regulate PTGS2 to participate in the cancer process." (PMID 36203533, 2022).
tumor (14 papers, 2014 to 2025). "Among the lipids upregulated in ARNT2 KO tumors were two carnitines associated with long-chain fatty acids, which can be used to generate energy for tumor growth via b-oxidation." (PMID 39184078, 2024). "This role as a tumor suppressor likely rests on its ability to drive the expression of genes that define the commitment to neuronal differentiation, thus ARNT2 loss may drive stemness." (PMID 39184078, 2024). "ARNT2 loss leads to tumor growth, and its upregulation prevents it." (PMID 39184078, 2024). "The increase in GBM tumor growth upon ARNT2 KO prompted us to investigate the potential role of ARNT2 as a tumor suppressor in GBM." (PMID 39184078, 2024). "We demonstrate that ARNT2, by promoting cell differentiation, functions as a tumor suppressor in GBM and possibly other tumors from neuronal origin." (PMID 39184078, 2024). "Next, using immunohistochemical staining (IHC), we observed that ARNT2 levels were downregulated in tumour tissue compared with the adjacent healthy tissue." (PMID 34469038, 2021). "In a previous study, a myriad of evidence has demonstrated the crucial roles of LINC01559 and ARNT2 in carcinogenesis and tumor progression." (PMID 34124046, 2021). "ARNT2 mRNA levels were higher in the cellular areas of the tumors than in the perinecrotic zones and barely detectable in tumor blood vessels." (PMID 29149419, 2018). "Altogether these results confirmed the functional relevance of the co-variation of ARNT2 expression with the tumorigenic/stem signature identified by tumor tissue and single cell transcriptome analysis." (PMID 29149419, 2018). "This indicates the major clinical impact of both MYB and ARNT2 to be tumor suppressive during early tumor development." (PMID 24639887, 2014). "Some studies have shown that ARNT2 plays a key role in tumor progression." (PMID 36203533, 2022). "In other studies, ARNT2, CREB3L1, GLI3, and PBX3 have been associated with tumor progression." (PMID 33924679, 2021). "Functional study showed that ARNT2 may inhibit the tumor progression by inducing tumor suppressor gene VHL and inactivating AKT signaling pathway." (PMID 34249704, 2021). "Importantly, this analysis revealed that ARNT2-expressing cells were especially enriched in the proliferative zones of the tumor." (PMID 29149419, 2018). "Moreover, ARNT2 expression correlated with a tumorigenic molecular signature at both the tissue level within the tumor core and at the single cell level in the patients’ tumors." (PMID 29149419, 2018). "Moreover, loss of ARNT2 leads to an increase of GBM cell proliferation in vivo and ARNT2 overexpression prevents it, implicating ARNT2 may act as a tumor suppressor in GBM." (PMID 39184078, 2024). "The other four (EPAS1, MXI1, ARNT2, and E2F1) relate to the signaling pathways involved in the processes of tumor formation and development." (PMID 40724805, 2025). "ARNT2 and PPARG showed positive correlations with the tumor grade of ESCC and were up‐regulated in G3 (poorly‐differentiated) compared to G1 (well‐differentiated)." (PMID 28904855, 2017). "Importantly, some the genes upregulated upon ZNF714 knockdown (PCDH20, STRA6, ARNT2, TIMP3) were previously shown to function as tumor suppressors." (PMID 37958512, 2023). "Some of these genes, which interfere with tumor cell growth/differentiation/migration/invasion (such as MYC, MET, PROM1, and PTK2), induce hypoxia (such as ARNT2, HIF3A, TGB2, MMP2, and POSTN) and genes regulating transcription via acetylation were downregulated upon pembrolizumab treatment." (PMID 32616706, 2020).
cardiovascular diseases (1 paper, 2022). "Activated ARNT2 in this study might be a therapeutic target to facilitate AVF maturation, as aryl hydrocarbons have been suggested as a therapeutic target in cardiovascular diseases." (PMID 35645372, 2022).
neurodegenerative disease (1 paper, 2018). A disorder of the central nervous system characterized by gradual and progressive loss of neural tissue and neurologic function. "This study has uniquely characterized the expression of ARNT2 in an inflammatory neurodegenerative disease model of MS." (PMID 30231889, 2018). "While the importance of ARNT2 in cell survival has been shown in models of ischemic injury, its expression patterns or role in chronic inflammatory and neurodegenerative disease of the CNS have not been characterized." (PMID 30231889, 2018).
ARNT2 also shares sentences with these, for which no sentence is quoted: oral squamous cell carcinoma (4 papers); Asperger Syndrome (2); gastric cancer (2); pancreas cancer (2); anxiety disorder (1); Ataxia (1); autism spectrum disorder (1); bipolar disorder (1); connective tissue disorder (1); diabetes (1); endometrial cancer (1); hepatoblastoma (1); hypospadias (1); Insulin resistance (1); lipoma (1); liver cancer (1); lymphoma (1); metabolic disease (1); multiple sclerosis (1); neurodevelopmental disorder (1); neurological disorders (1); non-small cell lung carcinoma (1); osteosarcoma (1); proliferative diabetic retinopathy (1); prostate carcinoma (1); renal cell carcinoma (1); retinoblastoma (1); rhabdomyosarcoma (1); skin cancer (1); skin cutaneous melanoma (1).
A further 2 diseases each share a sentence with ARNT2 in 1 paper.